AZGP1 (alpha-2-glycoprotein 1, zinc-binding)
Diseases named in the same sentence as AZGP1 in open-access papers (continued):
Sharing a sentence is not in itself a finding about the gene and the disease.
tumor (continued). "By measuring l-lactic acid production, extracellular acidification rates, and oxygen consumption rates (which reflects mitochondrial respiration) in PC3 cell lines before and after AZGP1 overexpression, we demonstrated that restoring AZGP1 expression reduces the glycolytic capacity of tumor cells." (PMID 41535762, 2026). "Blood plasma and tumor tissue were collected from the surgical mice at the study endpoint to assess whether tumor formation could lead to a reduction in plasma levels of AZGP1 and/or alter the expression of specific proteins." (PMID 41013181, 2025). "Consequently, the over-secreted AZGP1 acted as a mediator for tumor-surrounding WAT browning in a paracrine manner through the classical β-adrenergic receptor–cAMP–PKA pathway." (PMID 38245780, 2024). "We generated a xenograft tumour model to demonstrate that AZGP1 suppresses tumour progression." (PMID 38183356, 2024). "In addition, AZGP1 expression decreased in relation to increasing tumour stage of development, and low expression of AZGP1 was correlated with poor OS in patients with CCA." (PMID 38183356, 2024). "Collectively, these findings indicated that AZGP1 suppressed CCA tumour growth in vivo." (PMID 38183356, 2024). "AZGP1 is a secretory adipose factor which participates in metabolic processes such as lipolysis and glucose transport, acts as a tumor suppressor and may be involved in immune modulation." (PMID 38610911, 2024). "In agreement with this hypothesis, low AZGP1 expression level in PC3 and DU145 tumor xenografts is associated with increased expression of angiogenic proteins." (PMID 38659028, 2024). "MIIP downregulation promoted N-glycosylation and over-secretion of AZGP1 in tumor cells." (PMID 38245780, 2024). "AZGP1 overexpression significantly suppressed tumour growth in a xenograft mouse model." (PMID 38183356, 2024). "Together these results suggest that AZGP1 does not affect growth in vivo; however, loss of AZGP1 expression appears to promote increased microvessel density and tumor vascularization." (PMID 38659028, 2024). "We hypothesized that upregulation of AZGP1 in vivo would stimulate apoptosis and suppress tumour growth." (PMID 38183356, 2024). "It has been reported that AZGP1 inhibits tumor epithelial-mesenchymal transition (EMT), inhibits growth and activates apoptosis, but the role of AZGP1 in ICC remains unknown." (PMID 37669935, 2023). "AZGP1 protein expression was found to be lower in 72.97% of tumor tissues than in adjacent tissues." (PMID 37669935, 2023). "We found that the AZGP1 expression in tumor tissue is predictive of the time to CRPC." (PMID 32726925, 2020). "A low AZGP1 expression correlates with a worse pathological tumor stage and higher GS." (PMID 32726925, 2020). "We measured the expression of six different Zn-binding proteins in tissue microarrays (TMAs) from OPSCC patients by IHC in matched tumor and normal tissue, including: Lipocalin-1 (n = 63), AZGP1 (n = 68), albumin (n = 26), S100A7 (n = 53), S100A7 (n = 53), S100A8 (n = 51) and S100A9 (n = 50)." (PMID 31740720, 2019). "All of these showed that AZGP1 downregulated group generated less tumor foci." (PMID 31632499, 2019). "In the TME, data supports the conclusion that AZGP1 could function as a tumor suppressor gene through inhibition of ERK signaling." (PMID 31740720, 2019). "Due to the high homology between AZGP1 and MHC class I sequence and structure, AZGP1 might be involved in tumor proliferation and invasion by different mechanisms." (PMID 29357838, 2018). "The molecular mechanisms of AZGP1’s tumor suppressive properties are still unclear." (PMID 23935945, 2013). "This analysis took following factors in consideration: tumor location, tumor size, histological grade, AZGP1 expression levels, TNM stage (7th edition TNM classification) and whether or not a radical resection was performed." (PMID 23935945, 2013).
tumor (continued). "AZGP1 expression was significantly reduced at both the mRNA (P = 0.023) and protein levels (P = 0.019) in tumor tissue samples, compared with expression in matched adjacent non-tumor tissue samples." (PMID 23935945, 2013). "Our study suggests that AZGP1 might serve as a candidate tumor suppressor and a potential prognostic biomarker in gastric carcinogenesis." (PMID 23935945, 2013). "This suggests that AZGP1 indirectly plays a role in hindering tumor progression." (PMID 23935945, 2013). "Low expression of AZGP1 could be served as a tumor biomarker for poor differentiation and a predictor for poor prognosis of HCC patients." (PMID 22625427, 2012). "However, it was notable that high-grade tumours expressed significantly less AZGP1 than moderate-grade tumours." (PMID 24281110, 2010). "Invasive and migratory assays, along with assessments of epithelial–mesenchymal transition (EMT)-related proteins in the representative PC3 and 22RV1 cell lines, confirmed our hypothesis: low AZGP1 expression enhances cell invasion and migration, promoting tumor cell metastasis." (PMID 41535762, 2026). "Notably, the metastatic model revealed that low expression of AZGP1 promotes tumor metastasis." (PMID 41535762, 2026). "Therefore, whether AZGP1 functions as an oncogene or a tumor suppressor remains controversial, and it may play opposite roles in different tumor types." (PMID 38245780, 2024). "In addition to the highly abundant plasma proteins, DIGE analysis also revealed a number of proteins that were expressed in normal and/or tumor prostate tissue, and also one protein, namely zinc alpha 2 glycoprotein (AZGP1), which is predominantly expressed in the prostate." (PMID 29286311, 2017). "Our data showed that AZGP1 expression level was significantly higher in tumor tissues than in normal tissues in a Chinese population which was consistent with the TCGA data derived from America population, suggesting that it could serve as a general diagnostic biomarker in different populations." (PMID 25561225, 2014). "This may suggest AZGP1 may be involved in tumor recurrence and metastasis." (PMID 22625427, 2012). "By suppressing AZGP1 and increasing TGF-β1, EHMT2 contributes to an immunosuppressive tumor environment." (PMID 41366520, 2026). "To validate these findings, we performed RT-qPCR for AZGP1 in four cell lines, confirming that the expression in metastatic cell lines (PC3 and DU145) was low, while primary tumor cell lines (LNCaP and 22RV1) showed higher expression." (PMID 41535762, 2026). "BL tumor cells exhibited elevated expression of MGP (matrix Gla protein), AZGP1 (alpha-2-glycoprotein 1), AGR2 (anterior gradient protein 2), TFF3 (trefoil factor 3), and FGFR1 compared to EP and LP cells." (PMID 39955556, 2025). "Tumor-derived factors such as IL-6, TNF-α, IFN-γ, AZGP1, and PTHrP, and tumor-host interactions influence metabolic programs in adipose tissue, including browning, lipolysis, inflammation, and thermogenesis." (PMID 38245780, 2024). "Of the remaining 41 genes, three (PIGC, PKM and PPIB) were commonly upregulated with oncogenic potential and 31 were commonly downregulated among CP and PDAC-CP, of which, 3 (AZGP1, EGLN1 and GNMT) were tumour suppressors." (PMID 35854233, 2022). "Two down-regulated tumor-property-specific lncRNAs (XLOC_010739, G015949) was found to be correlated with 4 down-regulated genes (PRRT3, AL590560.1, AC114783.1 and AZGP1) (boxed in orange)." (PMID 32636408, 2020). "This is the first attempt to characterize the composition of OPSCC tumor tissue by trace elements using XFM and to demonstrate that Zn-binding protein AZGP1 is a potential biomarker for positive prognosis in HNSCC." (PMID 31740720, 2019). "In addition, AZGP1 expression was linked with PTEN deletion and might regulate the phosphatidylinositol-3 kinase (PI3K/AKT) pathway, which can trigger a cascade of responses to drive cell proliferation and tumor progression." (PMID 29357838, 2018).
tumor (continued). "Relative expression levels of the eight genes of interest (AZGP1, BIRC5, DHCR7, IL6ST, MGP, RBBP8, STC2, and UBE2C) were compared between paired whole tissue sections and tumor-enriched specimens." (PMID 25218890, 2014). "MAGE-C2/CT-10 should be added to the list of proposed prognostic tumor progression markers, including MUC1, AZGP1, EZH2, E2F3, Ki67, and CD10." (PMID 21754986, 2011). "By comparing AZGP1 expression between Met and non-Met subgroups, we further confirmed our findings that tumor cells with lower AZGP1 expression exhibited metastatic capability (P = 2.289 × 10–7)." (PMID 41535762, 2026). "The results indicated a significant negative correlation between AZGP1 expression and tumor metastasis, while CXCR4 showed a significant positive correlation." (PMID 41535762, 2026). "Once again, over-expression of AZGP1 did not affect tumor size, volume or weight, but did decrease tumor redness and microvessel density compared to controls, albeit to a slightly lesser degree compared to PC3 cells." (PMID 38659028, 2024). "When we analyzed tissue samples from 74 ICC patients, we found that 72.97% of tumor tissues had reduced or absent AZGP1 expression, which was consistent with the results in the TCGA and GEO databases." (PMID 37669935, 2023). "It has been revealed that AZGP1 could upregulate the expression of PTEN and regulate the PTEN/AKT pathway to suppress tumor development." (PMID 36831602, 2023). "We further constructed gene modules in AT2 (LUAD) and basal (LUSC) cells, which revealed that many tumor-related genes in cells from stage-I patients, including PIGR, AZGP1, BTG2, EGR1, and LMO3 in AT2 cells from LUAD, and AQP3, SPHK1, PPT1, and PDIA6 were found in basal cells from LUSC." (PMID 35027529, 2022). "KLK3, AZGP1 and PIP are AR regulated and reflect tumor AR activity." (PMID 34736512, 2021). "Furthermore, a list of genes, including AZGP1, KRT19, and PIGR, was identified as differentially expressed between TNBC and other tumor types, suggesting their potential use as discriminatory markers." (PMID 31134153, 2019). "Among the six Zn-binding proteins, AZGP1 was the only protein with significant differential expression levels amongst HPV-positive and HPV-negative samples, with higher median expression in tumor relative to normal in HPV-positive cases compared to HPV-negative cases." (PMID 31740720, 2019). "Kruskal-Wallis's analysis revealed that AZGP1 expression was significantly decreased by more than 2-fold in tumorous tissues, compared to that in adjacent non-tumorous liver tissues (P <0.001, t = -6.502)." (PMID 22625427, 2012). "There was significant difference in the average level of AZGP1 between tumor tissues and non-tumorous tissues (P = 0.001)." (PMID 22625427, 2012). "There were no statistical connections between AZGP1 expression and the rest clinicopathological parameters, such as patient age, gender, HBsAg, tumor size, tumor multiplicity, clinical stage and vascular invasion (P > 0.05)." (PMID 22625427, 2012). "In PC3 and DU145 mouse xenografts, over-expression of AZGP1 did not affect tumor growth." (PMID 38659028, 2024). "In addition, overexpression of AZGP1 did not have a significant impact on tumor growth of PC3, 22RV1, and DU145 xenograft models compared to vector controls with very low expression of AZGP1." (PMID 38659028, 2024). "In addition, 3 tumour suppressors genes were down regulated: GNMT, AZGP1 and EGLN1." (PMID 35854233, 2022). "Thus, silencing AZGP1 could be an efficient method to prevent metastasis and improve OS in CRC patients by delaying tumor progression." (PMID 31632499, 2019). "Similarly, over-expression of AZGP1 did not affect tumor growth for AR-positive 22Rv1 cells." (PMID 38659028, 2024).
tumor (continued). "Hence, the results revealed that the high-risk score may be an essential factor for B and T cell growth and differentiation leading to tumor immunosuppression, and the low expression of EZH2 and AZGP1 and high expression of IGF2BP2 were the main factors of tumor immunosuppression in the risk model." (PMID 33505420, 2020). "The MFP proteome was enriched for several immune-related and plasma proteins more indicative of inflammatory infiltration and chronic immune activation rather than tumor-specific remodeling including C1QB, CFH, MZB1, IGKV3-20, ORM2, ALB, and AZGP1." (PMID 41007761, 2025). "Albeit the roles of AZGP1 and IGF2BP2 in the immune response have not been investigated, our study was first to suggest that AZGP1 downregulation and IGF2BP2 upregulation may act as suppressors in tumor immune response in SCCHN." (PMID 33505420, 2020).
metabolic disorders (8 papers, 2014 to 2025). "Studies have shown that the AZGP1 gene can be inhibited by TNF-alpha and other genes related to the development of metabolic disorders." (PMID 35804531, 2022).
infection (5 papers, 2013 to 2025). The state of being infected such as from the introduction of a foreign agent such as serum, vaccine, antigenic substance or organism. "The expression of AZGP1 was up-regulated significantly after RD cells infection with AZGP1 lentivirus." (PMID 29357838, 2018). "Azgp1, with a constitutive expression of about 240 above the normalization level, continuously decreased its expression to about 210 at the peak of parasitaemia on day 8 p.i., and this level remained towards the end of the crisis phase of infection on day 11 p.i.." (PMID 40243929, 2025).
kidney disease (5 papers, 2013 to 2023). "Further research is needed to explore additional potential effects of increased AZGP1 in patients with kidney disease." (PMID 23849457, 2013). "Together these data show beneficial effects of elevated AZGP1 levels in fibrotic kidney disease and highlight a novel link to tubular cell lipid metabolism, which might open up new opportunities for CKD treatment." (PMID 35054830, 2022).
neurologic disorders (1 paper, 2025). "AZGP1 is considered a regulatory factor in metabolic functions, blood pressure regulation, neurologic disorders, and CVDs." (PMID 40026415, 2025).
respiratory diseases (1 paper, 2025). "Additionally, in respiratory diseases such as COPD, the RNA-binding protein Alpha-2-Glycoprotein 1 (AZGP1) downregulates GBP5, modulating epithelial hyperplasia during disease progression." (PMID 40788157, 2025).
AZGP1 also shares sentences with these, for which no sentence is quoted: type 2 diabetes mellitus (15 papers); diabetic nephropathy (10); Cachexia (9); Hypertension (6); cardiovascular disease (5); central obesity (5); COVID-19 (4); Impaired glucose tolerance (4); oral squamous cell carcinoma (4); End stage renal disease (3); endometriosis (3); atherosclerosis (2); chronic heart failure (2); dementia (2); hyperthyroidism (2); keratitis (2); liver disease (2); lung adenocarcinoma (2); lymph node metastases (2); multiple myeloma (2); oral cancer (2); ovarian carcinoma (2); psoriasis (2); Sepsis (2); uveal melanoma (2); adenocarcinoma (1); advanced heart failure (1); age-related macular degeneration (1); Alzheimer disease (1); amyotrophic lateral sclerosis (1).
A further 50 diseases each share a sentence with AZGP1 in 1 paper.